VILL (villin like)
Description:
Possible tumor suppressor.
Tractability: PROTAC: ubiquitination databases record sites on it.
Gene: Protein-coding gene on chromosome 3 (37,987,978 to 38,007,188, forward strand). Ensembl gene ENSG00000136059.
Subcellular location (Human Protein Atlas): Cytosol; Golgi apparatus
Gene Ontology:
Molecular function: phosphatidylinositol-4,5-bisphosphate binding; structural constituent of cytoskeleton; actin binding; actin filament binding
Biological process: actin filament severing; actin polymerization or depolymerization; barbed-end actin filament capping; cytoskeleton organization
Cellular component: actin cytoskeleton
Genetic constraint (gnomAD): Loss-of-function variants: 102 observed, 108.61 expected, observed/expected ratio (o/e) 0.94, 90% interval 0.8 to 1.11. The upper end of that interval is the gene's LOEUF score, 1.11, which puts it in group 4 of 6, group 1 being the genes least tolerant of losing a copy. Missense variants: 1,076 observed, 1,152.5 expected, observed/expected ratio (o/e) 0.93, 90% interval 0.89 to 0.98. Synonymous variants: 431 observed, 458.49 expected, observed/expected ratio (o/e) 0.94, 90% interval 0.87 to 1.02.
Homologues: Orthologues: chimpanzee VILL (99% identical), macaque VILL (94% identical), pig VILL (77% identical), guinea pig VILL (75% identical), dog VILL (74% identical), mouse Vill (72% identical), rat Vill (69% identical), tropical clawed frog vill (52% identical), zebrafish vill (49% identical), Drosophila melanogaster Gel (26% identical), Caenorhabditis elegans gsnl-1 (18% identical). Paralogues in human: VIL1 (47% identical), AVIL (45% identical), GSN (34% identical), SCIN (32% identical), SVIL (26% identical), FLII (22% identical), CAPG (15% identical).
Diseases named in the same sentence as VILL in open-access papers:
VILL is named in the same sentence as 6 diseases in open-access papers, as found by Europe PMC text mining. Sharing a sentence is not in itself a finding about the gene and the disease. The quoted sentences say what the papers report.
endometrial cancer (1 paper, 2025). Primary or metastatic malignant neoplasm involving the endometrium (mucous membrane that lines the endometrial cavity). "The low expression of CAPG, AVIL, and SVIL, together with the high expression of GSN, VILL, and FLII, were found to be significantly associated with poor overall survival in endometrial cancer patients." (PMID 39964147, 2025).
lung adenocarcinoma (1 paper, 2021). A carcinoma that arises from the lung and is characterized by the presence of malignant glandular epithelial cells. "Notably, we demonstrated that both high-MAL gene expression and low-VILL gene expression seem to synergistically confer survival advantages for patients with melanoma, lung adenocarcinoma, pancreatic adenocarcinoma, or renal cancer." (PMID 33672337, 2021).
tumor (1 paper, 2025). "Among the eight gelsolin superfamily genes, CAPG, VILL, and SVIL showed high associations with immune cell infiltration, highlighting their crucial roles in the tumor microenvironment (TME) and immunological function." (PMID 39964147, 2025). "Consequently, clinicopathological characteristics and the expression levels of GSN, SCIN, CAPG, VILL, VIL1, SVIL, and FLII were found to be closely associated with tumor stages in EC." (PMID 39964147, 2025).
VILL also shares sentences with these, for which no sentence is quoted: melanoma (1 paper); pancreatic adenocarcinoma (1); renal carcinoma (1).